CXCL9 (C-X-C motif chemokine ligand 9)
Diseases named in the same sentence as CXCL9 in open-access papers (continued):
Sharing a sentence is not in itself a finding about the gene and the disease.
tumor (continued). "Cytokines such as CXCL8, CXCL9, and CXCL10 are capable of attracting and activating immune cells, including macrophages and lymphocytes, causing their accumulation around the tumor." (PMID 38277205, 2024). "Of note, inhibition of CXCL9/10 production by epigenetic silencing or soluble inhibitors, has been shown to facilitate tumor development in cancer models and patients, supporting the importance of CXCL9/10 paracrine effect on immune cell recruitment." (PMID 38167224, 2024). "The TME of human ovarian tumors secretes CXCL9 in an IFNγ-dependent manner and thus recruits tumor-reactive T cells, conferring longer survival of patients and better response to checkpoint immunotherapy." (PMID 38786066, 2024). "Through its interaction with the receptor CXCR3, CXCL9 affects the behavior of various immune cells within the tumor, particularly T cells and NK cells." (PMID 38791448, 2024). "Histological evaluation of paraffin-embedded tumors demonstrated decreased tumor content following IT CXCL9/10-DC as monotherapy, or in combination with anti-PD-1, as determined by the ratio of PanC/K+ (tumor) areas to total tissue area." (PMID 38518770, 2024). "IT CXCL9/10-DC led to an increased depth of tumor penetration by CD4+ T cells when compared to CD8+ T cells." (PMID 38518770, 2024). "It is noteworthy to mention that tumor-infiltrating cDC1s are the major producers of CXCL9 and CXCL10 chemokine ligands that facilitate the recruitment of CD8+ T cells into the TME." (PMID 38360737, 2024). "IT CXCL9-DC or CXCL10-DC provided similar efficacy as compared to CXCL9/10-DC in the KPL-3M tumor-bearing mice." (PMID 38518770, 2024). "Ipsilateral tumor vaccination with IT CXCL9/10-DC resulted in the inhibition of contralateral tumor growth, suggestive of systemic immunity following local tumor vaccination." (PMID 38518770, 2024). "Like CXCL9, CXCL10 and CXCL11 expression, HLA-DR expression on tumor cells is tightly linked to IFN-γ signaling." (PMID 38822345, 2024). "For instance, CXCL9/10/11 chemoattract effector CD8+ T cells to the tumor microenvironment, making an argument for their promising role as biomarkers for a favorable outcome." (PMID 38928238, 2024). "Tumor vaccination with CXCL9/10-DC induced a statistically significant elevation in the concentrations of CXCL9 and CXCL10 within the TME at 24 h, surpassing levels observed with PBS control and Mock-DC." (PMID 38518770, 2024). "During the progression of COAD, studies have shown that the expression levels of certain chemokines, such as CXCL9 and CCL2, are closely associated with the tumor’s invasive behavior and prognosis." (PMID 38791448, 2024). "The mRNA and protein levels of the IFN-γ-induced chemokine CXCL9 were also upregulated in tumors from hsBCL9z96-treated CT26 tumor-bearing mice and MC38 tumor-bearing Bcl9/Bcl9l deficiency mice." (PMID 38811552, 2024). "LIF regulates CXCL9 in tumor-associated macrophages and prevents CD8+ T cell tumor-infiltration impairing anti-PD1 therapy." (PMID 38789520, 2024). "Using DIABLO, we showed that patients with high TC,57+ infiltration have an increased expression of CXCL9 in their tumor cells." (PMID 39001353, 2024). "Targeting Gsdmc in murine PDAC models reprograms the immunosuppressive tumor microenvironment, rescuing the recruitment of anti‐tumor immune cells through CXCL9." (PMID 39297408, 2024). "IT CXCL9/10-DC promoted an increase in CD8+ T cell infiltration into the tumor compared to the control." (PMID 38518770, 2024). "A study found that higher CXCL9 levels decreased T cell expression, which accelerated tumor growth in transgenic mice." (PMID 38745115, 2024). "Abrogation of endothelial Notch signaling modulates EC-derived angiocrine factors to enhance the pro-inflammatory activities of CAFs, which drive CXCL9/10-CXCR3-mediated T cell recruitment to inhibit tumor growth." (PMID 38947054, 2024).
tumor (continued). "CXCL9 upregulation in the stromal compartment of p16+/HPV- tumours relative to p16-/HPV- is suggestive of subtle amelioration of immune responses consistent with intermediate prognosis." (PMID 39328208, 2024). "Following YY001 treatment, the tumor tissue exhibited increased secretion of cytokines such as CXCL9, CXCL10, and CXCL11, which contribute to the recruitment of more T cells." (PMID 38560505, 2024). "The application of IFNγ neutralizing antibodies, knockdown of CXCL9/CXCL10 gene, or CXCR3 blockade of macrophages all cause the attenuation of anti-tumor immune response." (PMID 38787372, 2024). "Similar to a double-edged sword, CXCL9 not only inhibits tumor growth by recruiting CTL, but also contributes to cancer proliferation by recruiting Tregs, TAMs, and MDSCs, which are involved in immune tolerance in tumors." (PMID 38720340, 2024). "Other genes confirmed to be expressed in TAMs with anti-tumor and favorably prognostic functions, CXCL9 and CD169, were also enriched in bTAMs, further indicating the tumor suppressive properties of bM2-like TAMs." (PMID 39507421, 2024). "Overall, inhibition of the IGF signalling axis promotes TAM and CAF production of CXCL9/10 to facilitate CD8+ T cell recruitment to PDAC tumours." (PMID 39165364, 2024). "It was evident that IRF‐score is strongly associated with multiple chemokines and receptors in 12 tumours, in particular CCL5, CCR2/4/5, CXCL9/10/11 and CXCR3 (p < 0.05)." (PMID 38130025, 2024). "Elevated levels of CXCL9 and CXCL10 have been observed to be associated with heightened tumor CD8+ T cell density and enhanced patient survival across various cancer types." (PMID 38590525, 2024). "With this strategy, it is efficient encapsulation and release of multiple drug loads that can efficiently induce CXCL9 expression in macrophages, both in vitro and in vivo in a mouse tumor model." (PMID 38342608, 2024). "To further verify that macrophage C5aR controls CXCL9 expression and tumor progression, we treated WT and C5aR−/− tumor-bearing mice with clodronate liposomes, which have been widely used to deplete macrophages in vivo." (PMID 38098230, 2024). "Other identified biomarkers in the pretreated tumor microenvironment in this trial include CXCL9, CXCL10, CD8, and 12-chemokine signatures and tertiary lymphoid structures." (PMID 38540132, 2024). "The involvement of CXCL9 in various stages of tumor development and its impact on different cell types in the tumor microenvironment highlight its functional complexity." (PMID 38791448, 2024). "CXCL9 is important for recruitment of T cells and has been shown to correlate with anti-tumor activity." (PMID 39001353, 2024). "The extensively diffusion of this cytokine alters the tumor microenvironment through the induction of CXCL9, CXCL10, and CXCL11, which recruit effect immune cells such as natural killer (NK) cells, T cells, monocytes, and others to the tumor site." (PMID 39080467, 2024). "The C-X-C motif chemokine ligand 9 (CXCL9) and CXCL10, which are interferon γ (IFN-γ)-inducible chemokines, are predominantly secreted by tumor-residing CD103+ dendritic cells (DCs) and tumor-associated macrophages." (PMID 38518770, 2024). "CXCL9 is involved in immune and inflammatory responses and plays an important role in tumor immunosurveillance and antitumor immunity." (PMID 39334887, 2024). "In mouse xenograft models, combination therapy with an HMA and CPI led to higher levels of CXCL9/10, reversal of immune evasion, and potent tumor regression." (PMID 38302476, 2024). "Analysis of stained tumor sections revealed the greatest accumulation of immune cells at the edge of the tumor following IT CXCL9/10-DC." (PMID 38518770, 2024). "Five days following tumor implantation, AAV6 encoding CXCL9 or EGFP control transgene was injected intratumorally, with anti-PD-1 ICB (10 mg/kg) administered intraperitoneally for a total of 4 doses given every 72 h." (PMID 38997283, 2024).
tumor (continued). "In the tumor microenvironment of PDAC, Sin3B‐deficient tumor cells and the recruitment of CD8+ T cells establish a positive feedback loop mediated by IFNγ‐CXCL9/10." (PMID 39316363, 2024). "This suggests that CD8+ T cells infiltrate the tumor via the CXCL9/CXCL10-CXCR3 pathway and therefore T cell expression of CXCR3 is cruicial for their migration toward CXCL9/10 produced by TAMs." (PMID 38533720, 2024). "We also used computational image analysis to quantify and assess the distribution of CXCL9 protein in the tumor core (TC) and invasive margin (IM)." (PMID 38957805, 2024). "Consistent with accumulation of nAlb at tumor sites, we found a notable increase in the expression of genes associated with STING pathway activation, including Ifnb1, Cxcl10, Cxcl9, and Tnfa." (PMID 38766114, 2024). "CXCL9 is a pleiotropic chemokine that can have immunostimulatory effects within the tumor microenvironment but has been reported to be elevated in patients with ER-negative metastatic breast cancer." (PMID 39623404, 2024). "“Hot tumors”, which mostly have high levels and locally enriched expression of CXCL9, are closely related to inflammation and anti-tumor reactivities." (PMID 38957805, 2024). "NKs are recruited into the TME by CXCL9, where they utilize death receptor-mediated apoptosis and perforin/granzyme-mediated cytotoxicity to target tumor cells and inhibit primary tumor growth." (PMID 39845973, 2024). "The polarity of CXCL9 and SPP1 in TAMs was positively associated with increased tumor infiltration of T cells, B cells, and dendritic cells (DCs), although CXCL9 positivity was associated with better prognostic value compared to SPP1." (PMID 38542388, 2024). "The upregulated genes in PTCL‐TBX21 included Th1‐related genes, including CXCR3, CD38, INFG, CXCL9, CXCL11, IL27, and genes associated with tumor immunity, such as CD274 (PD‐L1), LAG3, and IDO1." (PMID 38234210, 2024). "Sin3B deficiency results in the upregulation of chemokines Cxcl9/10, thereby enabling the high levels of Cxcl9/10 in the tumor tissues to recruit more CXCR3‐expressing effector T cells." (PMID 39316363, 2024). "Within the TME, the CXCL9/10/11-CXCR3 signaling pathway has the potential to elicit anti-tumor immunity through various mechanisms." (PMID 38590525, 2024). "Chemotherapeutic treatment of tumor-bearing mice was reported to lead to intratumoral expression of CXCL9, CXCL10, and CCL5 chemokines which facilitate recruitment and infiltration of CD4+ and CD8+ T cells into the tumor bed." (PMID 38360737, 2024). "In pretreatment tumor tissue, response to nivolumab and ipilimumab correlated with higher messenger RNA (mRNA) expression of CXCL9 (P = 0.011), consistent with reported results in multiple tumor types." (PMID 39190534, 2024). "IT CXCL9/10-DC promotes T cell infiltration and activation in the tumor microenvironment and enhances antitumor efficacy of immune checkpoint blockade in murine NSCLC models." (PMID 38518770, 2024). "Herein, we develop a recombinant adeno-associated virus (AAV) gene therapy that enables focal and stable reconstitution of the tumor microenvironment with C-X-C motif ligand 9 (CXCL9), a powerful call-and-receive chemokine for lymphocytes." (PMID 38997283, 2024). "These include induction of CXCL9 expression, a strong prognostic biomarker in several tumours, and differentiation of bone marrow-derived myeloid cells, both of which can induce CD8+ T cell recruitment and activation." (PMID 39322643, 2024). "Literature suggests that the chemotactic draw of effector T cells into tumor sites, orchestrated by CXCL9 and CXCL10, aids in the establishment of a “hot” TME characterized by T cell inflammation." (PMID 39170612, 2024). "Although the DC vaccines had a limited lifespan, IT CXCL9/10-DC induced infiltration of both endogenous cDC1s and cDC2s into the tumor at 24 h." (PMID 38518770, 2024).
tumor (continued). "In our previous research, we explored the CXCL9 expression pattern in the TNBC tumor microarray (TMA), and found that CXCL9 was mainly expressed in immune cells, but rarely in tumor cells." (PMID 38957805, 2024). "We investigated the CXCL9 expression in different tumor regions including TC, IM, and both TC and IM." (PMID 38957805, 2024). "Notable among these transcripts are CXCL9,10, and 11, which are ligands for the tumor-suppressive CXCR3 receptor." (PMID 39717106, 2024). "Overexpression of CXCL9 MIG can also reduce tumor progression and metastasis via the inhibition of angiogenesis." (PMID 39451257, 2024). "The upregulation of CXCL9 contributed significantly to the formation of “hot” tumors, characterized by heightened immune cell infiltration and activity within the tumor microenvironment." (PMID 38962427, 2024). "Although a progressive decrement in CD8+ T cell tumor infiltration was observed in control mice from D14 to D23, CXCL9/10 vaccination induced progressive recruitment of CD8+ T cells to the tumor margin over time." (PMID 38518770, 2024). "This article consolidates the significance and prospects of CXCL9:SPP1 as a novel indicator for tumor development and prognosis, while also proposing future research directions and addressing potential challenges in this promising field." (PMID 38217023, 2024). "Evaluation of TDLNs following IT CXCL9/10-DC therapy in KPL-3M tumor-bearing mice showed enhanced proliferation of both CD4+ and CD8+ T cells, ascertained by Ki67+ staining, and an increased T cell effector polarization, determined by CXCR3 expression." (PMID 38518770, 2024). "Decreased IFN-I signaling pathway results in decreased Cxcl9/10 expression, leading to impaired T cell tumor recruitment to promote tumor immune evasion." (PMID 38995014, 2024). "Immune Response and Prognosis: CXCL9, CXCL10, and CXCL13 are linked to favorable prognosis due to their role in enhancing the immune response at the tumor site, suggesting their potential as biomarkers for immune contexture in cancer." (PMID 39546375, 2024). "First of all, CXCL9 and -10, generally known to be required for effector T cells trafficking into the tumor, were present in the majority of TME-derived secretomes." (PMID 39249543, 2024). "Using GL261 tumor cells as the target population for AAV6 transduction, significantly more T lymphocytes co-localized in the CXCL9 transduced tumor field as compared to EGFP at 24 h." (PMID 38997283, 2024). "Single-cell RNA sequencing (scRNA-seq) of sorted CD45+ tumor-infiltrating immune cells was conducted on D14 following IT CXCL9/10-DC and i.p. anti-PD-1 as monotherapies or in combination." (PMID 38518770, 2024). "CCL5 derived from tumor cells and C—X—C motif chemokine ligand 9 (CXCL9) secreted by IFN‐γ‐stimulated macrophages and DCs were critical for CD8+ T‐cell recruitment." (PMID 36599655, 2023). "We then performed immunohistochemical analysis in tumor sections that showed a higher proportion of CXCL9-dependent infiltrating CD3+ and CD8+ TILs in Pant samples, whereas they were in reduced numbers or confined to the periphery in control tumors." (PMID 37833072, 2023). "In fact, RT sustains CD8 T-cell recruitment into the tumor by inducing the expression of several factors, including IFNα, CXCL9, CXCL10, and CXCL11, as well as promoting extravasation by upregulating ICAM-1 and E-selectin on endothelial cells." (PMID 36831435, 2023). "Nivolumab was found to upregulate CXCL9 in metastatic RCC, and a transcriptome study of >1000 patients found that CXCL9 was the second-most important predictor of response to ICIs in multiple tumor types, including RCC." (PMID 37568390, 2023). "On the one hand, CXCL9 is commonly known as a chemokine with anti-tumor properties that contribute to effective T cell responses and immune infiltration, and it can serve as a favorable prognostic marker in PDA." (PMID 36980700, 2023).
tumor (continued). "When ctDNA detection was combined with the level of tumour mutational burden (TMB) and a tumour-derived interferon signature (including HLA-DRA, CXCL9/10/11, GZMA, PRF1, CCR5, IFNG, IDO1 and STAT1), the predictive value of the combined score was enhanced." (PMID 38201222, 2023). "It is generally accepted that a decline in production of chemokines such as CCL5 and CXCL9/10/11 in tumor stromal cells contributes to tumor promotion and even to ICI resistance." (PMID 37736764, 2023). "In consistency with these studies, ETP-treated and F30-HSCs exhibited higher levels of pro-inflammatory gene expression, such as IL-1β, IL-6, CXCL1 and CXCL9, as well as MMPs (for tumor metastasis) than controls." (PMID 37649614, 2023). "In the brain, elevated CXCL9 expression was selectively detected in the tumor bearing hemisphere transduced with AAV-CXCL9, with minimal signal observed in the contralateral hemisphere in both GL261 and KR158 model systems." (PMID 38014191, 2023). "The frequency of tumor cells expressing apical Cxcl9/Cxcl10 was significantly decreased in KPC recipients of 1045 T cells or 1045 T cells + CD40 agonist." (PMID 36472588, 2023). "The pan-HDACi rodempsin was reported to increase the expression of chemokines CCL5 and CXCL9 and 10 by tumor and stromal cells, increasing tumor infiltration with T cells and thereby improving the antitumor immune response." (PMID 38258065, 2023). "Transgene CXCL9 expression appears to be stable, as signal intensity was consistent in AAV6-CXCL9 transduced tumors at both the 1- and 2-week time points in each tumor model." (PMID 38014191, 2023). "For example, CXCL9 is a chemokine that attracts effector T cells expressing CXCR3 into the tumor microenvironment." (PMID 37926766, 2023). "Within the tumor, Batf3-dependent cDC1s that express CXCL9 and CXCL10 are required for effector T cell chemo-taxis." (PMID 37377970, 2023). "Mechanistically, T-αFGL2 cell treatment increased the number of CD69+CD8+ brain-resident memory T cells in tumor-bearing mice via a CXCL9/10 and CXCR3 chemokine axis." (PMID 36759517, 2023). "CXCL10 and CXCL9 are antitumour chemokines that can inhibit cancer cell proliferation as well as regulate immunity to recruit a variety of immune cells to kill tumour cells." (PMID 36980202, 2023). "Natural killer (NK) cells and Th1 cells share CXCR3 receptors and exert anti-tumor effects in response to stimulation by the specific ligands CXCL9, CXCL10, and CXCL11." (PMID 37063892, 2023). "In a study, MEK inhibitors such as trametinib were shown to restore the induction of CXCL9 and 10 when treated with the platinum salt and pemetrexed doublet, resulting in a reduced tumor progression and increased survival." (PMID 37108738, 2023). "Nevertheless, LAC injection in tumor effectively liberated IL-12 and IFN-γ and thus elevating downstream chemokines CXCL-9 and CXCL-10, particularly in RNF8 deficient mice." (PMID 37391451, 2023). "In the uni-cox analysis, CXCL9 expression, age, clinical stage, histological subtype, histologic grade, tumor invasion, and residual tumor were closely related to OS in UCECC patients." (PMID 36845675, 2023). "Based on the bioinformatics strategy, it showed that a higher ratio of anti-tumor immune cells characterized CXCL9 high expression." (PMID 36845675, 2023). "Using GL261 tumor cells as the target population for AAV6 transduction, significantly more T lymphocytes co-localized in the CXCL9 transduced tumor field as compared to EGFP at 24 hours." (PMID 38014191, 2023). "CXCL9, an inflammatory chemokine, has shown inhibitory effects on NSCLC tumor growth and metastasis by reducing tumor-associated angiogenesis." (PMID 37816585, 2023). "By activating the GNAS-PKA axis, MC1R inhibits interferon-gamma induced CXCL9/10/11 transcription, thus impairing T cell infiltration into the tumor microenvironment." (PMID 37714844, 2023).